PLTP (phospholipid transfer protein)
Diseases named in the same sentence as PLTP in open-access papers (continued):
Sharing a sentence is not in itself a finding about the gene and the disease.
Sepsis (14 papers, 2016 to 2025). Sepsis is defined as life-threatening organ dysfunction caused by a dysregulated host response to infection. "In previous studies, PLTP was believed to have anti-inflammatory effects and reduce the risk of sepsis." (PMID 35874944, 2022). "In support of the cause-effect relationship between PLTP expression and antimicrobial defense, the resistance of Pltp−/− mice to the harmful consequences of sepsis induced by polymicrobial infection was compared with that in WT mice." (PMID 28596518, 2017). "By contrast, high PLTP activity has been linked to inflammation, particularly in sepsis patients." (PMID 38130330, 2023). "Our data support the role for HDL and PLTP in the elimnation of LPS during human peritonitis with sepsis." (PMID 40682387, 2025). "The high‐density lipoprotein (HDL) and the phospholipid transfer protein (PLTP) have been demonstrated to enhance endotoxin elimination and inactivation in animal models of sepsis." (PMID 40682387, 2025). "Our data support the role of HDL and PLTP in the elimination of LPS during human peritonitis with sepsis." (PMID 40682387, 2025). "In this study, we established the in vivo and in vitro sepsis model with the recombinant PLTP treatment." (PMID 38584827, 2024). "Sepsis-induced cardiac inflammatory responses lead to pyroptosis, and our results showed that rh PLTP treatment inhibited inflammatory factor release in mice with sepsis." (PMID 38584827, 2024). "Potential HDL-directed interventions for treatment of sepsis include apolipoprotein A-I-based therapies, recombinant PLTP, and CETP inhibition." (PMID 36361756, 2022). "We similarly found that PLTP activity was significantly higher in sepsis patients at 6.5 pmol/h compared to controls at 5.0 pmol/h." (PMID 35071235, 2021). "LCAT activity, LCAT concentration and CETP activity were significantly lower, while PLTP activity was significantly higher in ICU sepsis compared to ICU control patients." (PMID 35071235, 2021). "Elevated PLTP activity was also reported in patients with severe sepsis and during the acute-phase response induced by infection." (PMID 34778311, 2021). "It supports the protective role of PLTP in neutralizing LPS in the context of septic shock, and it is in line with previous studies in animal models of endotoxemia or sepsis." (PMID 34778311, 2021). "In further support of the antimicrobial effect of PLTP, PLTP-knocked out mice were found to be less able than wild-type mice to fight against sepsis." (PMID 28596518, 2017). "First, metabolism of LPS and especially its detoxification by PLTP and lipoproteins have been demonstrated to be critical in sepsis shock." (PMID 28848554, 2017). "Recombinant human plasma PLTP (rh PLTP) has been used to prevent bacterial growth and treat sepsis." (PMID 38584827, 2024). "Moreover, we also found that rh PLTP treatment inhibited the activation of the NLRP3 inflammasome/GSDMD signaling pathway in the heart tissue of mice with sepsis." (PMID 38584827, 2024). "Moreover, PLTP plays a key role in regulating immune responses, and it is directly linked to a wide range of inflammatory diseases, including bacterial infection-induced sepsis, which might be dependent on its ability to accelerate the reverse LPS transport pathway." (PMID 38584827, 2024). "It was reported that PLTP can alleviate LPS-mediated inflammation and sepsis." (PMID 38584827, 2024). "PLTP was increased during sepsis, and PLTP levels correlated with inflammatory markers." (PMID 35071235, 2021). "Indeed, PLTP activity was found elevated in sera from patients with acute inflammation and clinical severe sepsis." (PMID 29565987, 2018). "In an attempt to satisfy the long-felt, but unmet needs to prevent and treat sepsis, the present study aimed to demonstrate that recombinant human PLTP could be a potential therapeutic agent." (PMID 28596518, 2017).
Sepsis (continued). "Finally, and in further support of the antimicrobial effect of PLTP, PLTP-knocked out mice were found to be less able than wild-type (WT) mice to fight against sepsis." (PMID 28596518, 2017). "Considering the increasing plasma PLTP activity in patients with endotoxemia or sepsis, we hypothesized that PLTP play key protective roles in LPS induced inflammatory responses." (PMID 26857615, 2016). "Indeed, the increased capacity of PLTP to neutralize LPS might explain the protective effect previously reported in sepsis." (PMID 34054798, 2021). "Although earlier studies described the production of human recombinant PLTP (rhPLTP) in eukaryotic cells, only low levels of active rhPLTP could be produced in bioreactors, thus hampering the possibility of using it at therapeutic levels in sepsis." (PMID 28596518, 2017). "Several HDL-associated enzymes, including phospholipid transfer protein (PLTP) and cholesterol ester transfer protein (CETP), undergo profound changes during sepsis." (PMID 36361756, 2022). "In previous works, we demonstrated that PLTP played a pivotal role in the RLT pathway and overall protection against endotoxemia and sepsis ex-vivo and in animals models." (PMID 34054798, 2021). "We highlighted the critical role of the phospholipid transfer protein (PLTP), a member of the lipid transfer/LPS binding protein (LT/LBP) family, in LPS metabolism and beyond in sepsis." (PMID 28848554, 2017). "Hence, we aimed to investigate the relevance of lipoprotein‐mediated LPS elimination in patients with acute peritonitis and sepsis by analysing the relationships between HDL, PLTP and LPS burden (mass and activity)." (PMID 40682387, 2025). "However, the link between HDL, PLTP, LPS elimination, reduced inflammation and improved outcome was not straightforward as LPS is not the only driver of inflammation in patients with sepsis." (PMID 40682387, 2025). "Furthermore, lipid transfer proteins such as PLTP and CETP are significantly altered during sepsis." (PMID 35071235, 2021).
diabetes (13 papers, 2008 to 2025). "Likewise, plasma PLTP activity was positively and independently associated with hsCRP taking account of either the presence of diabetes (Model B1) or of fasting glucose (Model B2)." (PMID 29587751, 2018). "Of further relevance, genetic variation in PLTP, a lipid transfer protein that is able to convert HDL into larger and smaller HDL particles, affects HDL particle distribution, whereas we proposed earlier that higher plasma PLTP activity may predict increased diabetes risk." (PMID 32245262, 2020). "PLTP activity was positively related to large HDL particles in patients with type 2 diabetes mellitus and positively correlated with the concentration of HDL particles containing Apo AI, but not Apo AII in patients with low HDL and CVD." (PMID 28930174, 2017). "PLTP expression is increased in different pathologies associated with increasing risk of CHD, such as obesity, insulin resistance, and types I and II diabetes." (PMID 22897926, 2012). "The elevated plasma PLTP activity in patients with type 2 diabetes mellitus is positively correlated with the carotid intima-media thickness." (PMID 18509527, 2008). "Conversely, some studies in the diabetes-relevant field showed an opposite trend in PLTP." (PMID 39589852, 2024). "Finally, PLTP activity is closely related to obesity, diabetes mellitus, insulin resistance, left ventricular systolic dysfunction, and intima-media thickness." (PMID 19948027, 2009). "Plasma PLTP activity is elevated in patients suffering from diabetes mellitus type 1 and type 2." (PMID 18509527, 2008). "Elevated plasma PLTP activity is considered as a novel marker of cardiovascular disease susceptibility, and is positively associated with left ventricular systolic dysfunction in patients with CHD and the carotid intima-media thickness in type 2 diabetes mellitus." (PMID 28930174, 2017). "However, plasma PLTP activity is positively associated with serum alanine aminotransferase and aspartate aminotransferase, two enzymes considered as predicts for NAFLD, in diabetes patients, and it has been suggested that PLTP may be a marker for NAFLD." (PMID 22897926, 2012). "In subsidiary analyses with BMI in addition to age, sex, the presence of diabetes, NEFA, total cholesterol and triglycerides as dependent variables, plasma PLTP activity but not ANGPTL4 was independently associated with BMI (β = 0.239, p = 0.05 and β = 0.137, p = 0.23, respectively; data not shown)." (PMID 29587751, 2018). "Given the relevance of PLTP and LCAT for altered HDL remodelling and triglyceride metabolism in diabetes, we decided to include both diabetic and non-diabetic subjects in the present study." (PMID 27581838, 2016).
Obesity (13 papers, 2009 to 2026). Accumulation of substantial excess body fat. "Overall, our study demonstrates that PLTP deficiency leads to less efficient detoxification of LPS but, also, to an exacerbated inflammatory response in the context of obesity and insulin resistance." (PMID 36362012, 2022). "We show here that PLTP deficiency worsens HF-diet induced obesity and insulin resistance in mice through mechanisms involving alterations of plasma triglyceride (TG) clearance, the inflammatory response and lipoprotein-mediated transport of gut-derived LPS." (PMID 36362012, 2022). "Additional studies in humans and mice have shown that there is an association between PLTP genetic variants and obesity-related phenotypes." (PMID 22768054, 2012). "The mRNA levels and the activity of PLTP have been consistently associated with obesity." (PMID 22768054, 2012). "Moreover, some studies have demonstrated an increased PLTP activity associated with obesity and metabolic syndrome in humans, whereas others have suggested that PLTP deficiency could lead to an improvement in tissue and whole-body insulin sensitivity in mice." (PMID 36362012, 2022). "Our findings further showed an upregulation of LAMTOR1 and PLTP (phospholipid transfer protein) in severe obesity." (PMID 41077621, 2026). "This study aimed to investigate the influence of PLTP on low-grade inflammation, obesity and insulin resistance in relationship with LPS intestinal translocation and metabolic endotoxemia." (PMID 36362012, 2022). "Despite its potential beneficial impact on LPS clearance, the role of PLTP in the onset of obesity and inflammation remains controversial." (PMID 36362012, 2022). "Also, an overexpression of PLTP mRNA was observed in the omental fat in both men and women with obesity." (PMID 41077621, 2026). "However, the impact of PLTP on inflammation induced by gut-derived LPS in a context of a HF diet and obesity is still unclear." (PMID 36362012, 2022). "What’s more, some key enzymes involved in HDL metabolism, such as cholesteryl ester transfer protein (CETP), lecithin/cholesterol acyltransferase (LCAT), hepatic lipase (HL) and protein phospholipid transfer protein(PLTP), are changed in people with obesity who have insulin resistance." (PMID 31842884, 2019). "In addition, although both plasma ANGPTL4 and PLTP activity were expectedly correlated with obesity and NEFA, ANGPTL4 was inversely correlated with total cholesterol and LDL cholesterol, whereas PLTP activity was significantly correlated with triglycerides." (PMID 29587751, 2018). "In addition, PLTP activity in plasma is elevated in IR and T2DM in association with high plasma TG and obesity." (PMID 22584085, 2012). "Other genes within the magenta module play a role in metabolic functions and obesity including genes that code for lipase (LIPA), phospholipid transfer protein (PTLP), and lipid metabolism (e.g., LPIN1)." (PMID 32151267, 2020). "In humans, PLTP activity has been shown to be positively and independently related to coronary heart disease (CHD) In addition, previous studies showed that PLTP activity was increased with aging, obesity, type 1 and type 2 diabetes." (PMID 19948027, 2009). "Thus, we suggest that PLTP might have a specific preference for plasma PG remodeling independent of the obesity-related metabolic status." (PMID 36362012, 2022).
coronary artery disease (9 papers, 2009 to 2022). "Polymorphisms of APOC1 (p = 0.01), F2 (p = 8 × 10−8), LPA (p = 0.001), and PLTP (p = 0.0009) showed significant individual effects on the predisposition to coronary artery disease." (PMID 35203469, 2022). "ppGalNAc-T2 has been shown to regulate high-density lipoprotein cholesterol (HDL-C) metabolism by O-glycosylation of phospholipid transfer protein (PLTP) and is suggested to associate with dyslipidemia and coronary artery disease (CAD)." (PMID 33218200, 2020). "PLTP activity is a risk factor for coronary artery disease and PLTP also plays a role in inflammation and oxidative stress." (PMID 27250500, 2016). "It has been reported that phospholipid transfer protein (PLTP) is an independent risk factor for human coronary artery disease." (PMID 22897926, 2012). "Furthermore, our study revealed, for the first time, that the rs6065906-T of PLTP is associated with the increased risk of coronary artery disease." (PMID 35203469, 2022). "Some studies found that plasma PLTP activity was inversely correlated with HDL-C levels in humans with coronary heart disease (CHD) or premenopausal women." (PMID 28930174, 2017). "The present study is the first to show that lipid-associated GWAS loci such as rs4420638 of APOC1, rs3136441 of F2, rs55730499 of LPA and rs6065906 of PLTP are susceptibility markers for coronary artery disease regardless of sex, age, and body mass index." (PMID 35203469, 2022). "We found that four polymorphisms such as rs4420638 of the APOC1 gene, rs3136441 of the F2 gene, rs55730499 of the LPA gene, and rs6065906 of the PLTP gene were significantly associated with the risk of coronary artery disease regardless of sex, age, and body mass index." (PMID 35203469, 2022). "It was also reported that possession of the rs2294213 minor allele could increase HDL-C independent of triglycerides, but it remains unknown whether this polymorphism could influence PLTP activity and is linked with coronary heart disease(CHD) or not." (PMID 19948027, 2009).
dyslipidemia (9 papers, 2015 to 2024). "To establish the in vivo relevance of these observations, we used an established mouse model of dyslipidemia, i.e., phospholipid transfer protein (PLTP)-deficient mice." (PMID 28765208, 2017). "Furthermore, we investigated the relationship between serum phospholipid transfer protein (PLTP) expression/activity and serum lipid concentration, and the results suggested that Pltp is a causative gene for dyslipidemia in C3H-S mice." (PMID 37620514, 2023). "In contrast, the positive association between PLTP activity and LPS reported here might be related to the increase in PLTP activity documented in patients with metabolic syndrome, further suggesting the presence of metabolic endotoxemia in our cohort." (PMID 38984349, 2024). "HDL CEC and plasma PLTP activity were positively correlated, and this association was also observed in participants with and without metabolic syndrome." (PMID 38130330, 2023). "The inhibition of CETP and PLTP could be expected to treat psoriasis with dyslipidemia in the future." (PMID 35982498, 2022). "Its mechanism of action is possibly related to the inflammatory alterations and dyslipidemia induced by increased expression of CETP and PLTP in mice with psoriasis." (PMID 35982498, 2022).
endotoxemia (9 papers, 2016 to 2025). "Although HDL pool size is considered as the decisive factor in LPS clearance in vivo, our findings suggested that PLTP other than HDL pool size is the primary cause to maintain the survival of mice in lethal endotoxemia." (PMID 26857615, 2016). "Indeed, after studying a model of PLTP-deficient mice, we previously reported that PLTP reduced host susceptibility to endotoxemia." (PMID 34054798, 2021). "Consequently, our findings clarified that the LPS neutralization role of PLTP was the main cause of the protective effects of PLTP in endotoxemia." (PMID 26857615, 2016). "Most of the protective roles of lipoproteins and PLTP on inflammation were observed in models of acute increase in endotoxemia induced by intravenous or intraperitoneal injections of LPS." (PMID 36362012, 2022). "It has also been shown that PLTP can protect mice from lethal endotoxemia independently of the HDL pool by neutralizing LPS and preventing the growth of gram-negative bacteria." (PMID 32084157, 2020). "The survival rate was closely related to plasma PLTP activity, strongly indicating that plasma PLTP was the key protective factors to mice survival in lethal endotoxemia." (PMID 26857615, 2016). "In the present study, we investigated the effects of PLTP expression on mice survival rate of lethal endotoxemia and the role of PLTP on LPS induced NFκB activation in macrophage." (PMID 26857615, 2016). "To summarize, PLTP protected mice from the attack of accumulated circulatory LPS, and subsequently increased the survival rate in lethal endotoxemia via its LPS neutralization capability." (PMID 26857615, 2016). "Our data highlighted the finding that PLTP is the primary extracellular protective protein to survival in lethal endotoxemia and to repress LPS induced inflammatory responses." (PMID 26857615, 2016). "In addition to lipoproteins, plasma proteins such as phospholipid transfer protein (PLTP) contribute to the control of endotoxemia." (PMID 36362012, 2022). "PLTP displayed a strong protective effect on lethal endotoxemia in mice survival study." (PMID 26857615, 2016). "Therefore, to clarify the role of active PLTP in endotoxemia, we conducted the present study and found that PLTP displayed a strong protective effect on lethal endotoxemia in mice survival study." (PMID 26857615, 2016). "Interestingly, high plasma PLTP activity was reported in septic patients as well as in experimental endotoxemia in humans, and increased PLTP levels could also be observed in a mouse model of infection." (PMID 34712716, 2021).
glioma (8 papers, 2019 to 2023). A benign or malignant brain and spinal cord tumor that arises from glial cells (astrocytes, oligodendrocytes, ependymal cells). "As a result, PLTP was identified as a novel glioma-associated protein that may be involved in the progression of human glioma." (PMID 38022651, 2023). "A high PLTP protein expression level is registered in clear cell renal cell carcinoma patients and is a growth/migration stimulator of glioma cells." (PMID 36289879, 2022). "In particular, the study performed on brain tissue of glioma patients showed a correlation between PLTP expression and the tumour grade." (PMID 31963743, 2020). "PLTP expression was increased in Grade IV human glioma relative to low grade glioma, and knockdown in vitro lead to the decreased migration of glioblastoma tumour cells." (PMID 31019223, 2019). "PLTP is differentially expressed in many kinds of tumors, such as prostate cancer, ovarian cancer, breast cancer, lung cancer, gastric cancer and glioma." (PMID 35468826, 2022). "Moreover, the differential expression of PLTP is documented in multiple types of tumours, including prostate, ovarian, breast, lung carcinoma and glioma." (PMID 31963743, 2020). "Overexpression of PLTP protein could promote growth and migration of human glioma cells." (PMID 32735728, 2020).